GUSB (glucuronidase beta)
Diseases named in the same sentence as GUSB in open-access papers (continued):
Sharing a sentence is not in itself a finding about the gene and the disease.
GUSB also shares sentences with these, for which no sentence is quoted: colorectal cancer (2 papers); celiac disease (1); cholesteatoma (1); Cirrhosis (1); cutaneous melanoma (1); developmental delay (1); endocarditis (1); goiter (1); hearing loss (1); heart abnormalities (1); hemangioma (1); hydrops (1); influenza (1); lentivirus infection (1); leukaemia (1); Lipid storage disease (1); liver diseases (1); Lysosomal disease (1); metastatic colorectal cancer (1); Morquio A disease (1); Mucopolysacchariduria (1); neurological disorders (1); neuronal ceroid lipofuscinosis (1); Niemann-Pick disease type C (1); ovarian tumours (1); pancreatic adenocarcinoma (1); pancreatic cancer (1); papillary thyroid carcinoma (1); pneumonitis (1); prostate adenocarcinoma (1).
A further 7 diseases each share a sentence with GUSB in 1 paper.